STAT1 (signal transducer and activator of transcription 1)
Diseases named in the same sentence as STAT1 in open-access papers (continued):
Sharing a sentence is not in itself a finding about the gene and the disease.
COVID-19 (continued). "Correlation plots between TMPRSS2 and commonly upregulated genes were representively shown for OAS1, STAT1 and IRF7 from COVID-19 vs. healthy PBMNCs." (PMID 40055791, 2025). "Despite their different effects on COVID-19 prognosis and their use of distinct receptor complexes, in cells, both type I and type III IFNs induce activation of STAT1, STAT2, and STAT3, as well as a similar subset of IFN-responsive genes." (PMID 40980495, 2025). "Furthermore, the identification and better underpinning of altered signaling pathways such as STAT-1 and AKT/AMPK could have several therapeutical implications, not only in COVID-19 but also in other thrombotic states associated with a wide spectrum of infectious diseases." (PMID 36902151, 2023). "Inspection of a previously published spatial data set of alveolar tissue (which did not discriminate between mild and severe DAD) confirmed upregulation of STAT1, CXCL10, BAFF, and TRAIL in COVID-19." (PMID 36472908, 2023). "ISG15, STAT1 and MX1 are the most conserved up-regulated genes across COVID-19 datasets of immunological cells." (PMID 36553678, 2022). "In large airway tissues, genes related to the mucosal layer (MUC4, MUC5AC, MUC5B) as well as cytokine-mediated signaling pathway genes (CCL20, CXCL1, CXCL6, CXCL6, MMP1) and type I interferon genes (IFIT3, ISG15, STAT1, MX1) were upregulated in COVID-19." (PMID 35233546, 2022). "In neutrophils, phospho-STAT1 and phospho-ERK distinguished healthy donors for patients with COVID-19." (PMID 35421120, 2022). "In the COVID-19 pathway, the SARS-CoV-2 receptors ACE2 and NRP1, some immune molecules such as IL-2, STAT1, and some complement molecules are the targets of tuftsin." (PMID 35402510, 2022). "STAT1 and STAT2 have higher activity in moderate patients than severe patients, suggesting a possible delay in the interferon response in severe COVID-19 patients." (PMID 34603282, 2021). "Targeted proteomics to measure abundance levels of MX1, ISG15, STAT1, RIG-I, and CXCL10 detected proteomic signatures of interferon-mediated antiviral signaling that differentiated COVID-19-positive from COVID-19-negative cases." (PMID 34400346, 2021). "Lastly, STAT1 and IFANR1 were identified as potential targets for COVID-19 treatment and were reported by another group as well." (PMID 33413329, 2021). "During COVID-19, SARS-CoV-2 nucleocapsid (N) protein binds to STAT1/STAT2 with the downstream kinases and inhibits their phosphorylation." (PMID 34603282, 2021). "When we directly compared COVID-19 and influenza, NFKB1, NFKB2, and TNF were up-regulated in COVID-19, whereas STAT1, TLR4, and genes for immunoproteasome subunits were up-regulated in influenza." (PMID 32651212, 2020). "NFKB1, NFKB2, IRF1, and CXCR3 were specifically up-regulated in COVID-19, and CXCL10, STAT1, TLR4, and genes for class II HLA and immunoproteasome subunits were specifically up-regulated in influenza." (PMID 32651212, 2020). "In conclusion, in COVID-19 the EGCG/GTE supplementation should be advantageous because of their multitarget action as regulators of both transcription factor (i.e., STAT1, STAT3, NF-κB, Nrf2) activities and expression of their target genes." (PMID 32708322, 2020). "Next, we measured the individual phosphorylation of STAT3, STAT1, JNK, p38, and IRF3 proteins and found them all to be increased in COVID-19 neutrophil whole cell lysates; however, it should be noted that the total levels of these proteins were not evaluated." (PMID 33003471, 2020). "Three patients in the severe COVID-19 group demonstrated strongly neutralizing anti-IFN-α AAbs, with titers exceeding 20,000 ng/mL, IC50 values ranging from 5000 to 68,000, and inhibition of IFN-α-induced STAT1 phosphorylation as assessed by flow cytometry." (PMID 40733719, 2025).
COVID-19 (continued). "The results suggest that IL27 induces a robust STAT1-dependent pro-inflammatory and antiviral response in an IFN-independent manner in COVID-derived PBMCs and monocytes as a function of a severe clinical course of COVID-19." (PMID 37310504, 2023). "Specifically, the dysfunctions of STAT1 and STAT3 induced by SARS-CoV-2 proteins may be the foundation of severe COVID-19 pathophysiology." (PMID 37261353, 2023). "The phosphorylation of STAT1 was reportedly strengthened in severe COVID-19 cases that failed to induce transcription of interferon-stimulated response elements (ISRE) by unbalanced JAK/STAT signaling." (PMID 38162574, 2023). "FOXC1, YY1, GATA2, FOXL, STAT1 and STAT3 are important TFs for COVID-19." (PMID 37261353, 2023). "On the other hand, the inflammatory NOTCH2-IL24 interaction which induces STAT1 and STAT3 to regulate cell proliferation and survival and the inhibitory interactions CTLA4-CD86 and HAVCR2-LGALS9 were unique to patients with COVID-19." (PMID 36992700, 2023). "The level of mRNA encoding STAT1 and STAT3 is elevated in COVID-19 patients, regardless of disease severity, and the results suggest that IL27 signaling is activated in response to SARS-CoV-2 infection." (PMID 37310504, 2023). "STAT1, MAPKAP2, CREB and IκBα were also increased in severe COVID-19 in both T cell populations." (PMID 35421120, 2022). "All signaling molecules of the IFN-I downstream pathway and IRFs (i.e., JAK-1, TYK-2, STAT-1, STAT-2, IRF-3, and IRF-7) showed very reduced expression levels in COVID-19 patients with the severe condition compared to healthy individuals at both RNA and protein levels." (PMID 35842705, 2022). "Generally, SARS-CoV-2 inhibits STAT1 and IFNs, resulting in the activation of the STAT3 pathway as a dominant signaling pathway, which could result in COVID-19 complications." (PMID 36111104, 2022). "Furthermore, results evidenced that COVID-19-positive patients with higher expressions of JAK2 and STAT1 showed increased MX1, MX2, ISG15, and OAS1 mRNA levels." (PMID 36298734, 2022). "SARS-CoV-2 mediated inhibition of STAT1, and the subsequent shift to a STAT3-dominant signaling may lead to the proinflammatory conditions most commonly observed in hospitalized COVID-19 patients." (PMID 36273032, 2022). "Furthermore, STAT1 (21,435th → 32nd), STAT2, EGFR, and IRF9 (2455th → 36th) are involved in interferon signaling and have been suggested in numerous COVID-19 studies." (PMID 36291657, 2022). "Moreover, a single cell transcriptional study performed in PBMCs from patients with COVID-19 suggests that IFN-α and IFN-γ function in T cells and DCs to promote disease severity through activating STAT1." (PMID 36419185, 2022). "Another study showed that Shufeng Jiedu prescription may prevent COVID-19 through its active ingredients likely quercetin, luteolin, wogonin, and kaempferol by targeting TNF, IL-10, IL-2, IL-6, STAT1, and CCL-2." (PMID 34861881, 2021). "TF activity analysis indicated a robust regulation by IRF2/IRF9 and STAT1/2 for this cluster of cells, within both severe and non-severe COVID-19." (PMID 34721400, 2021). "Intriguingly, despite the absence of autoantibodies directed at type I interferons, nearly all participants who developed severe COVID-19 failed to induce STAT1, STAT2, IRF1, and IRF9 expression (among other IFN-stimulated genes)." (PMID 34352228, 2021). "Even individuals who had milder disease and limited requirement for respiratory support at the time of nasal swab, but later went on to develop severe or fatal COVID-19 (swab WHO 1–5, peak WHO 6–8), already had diminished STAT1 expression at the time of nasal swab." (PMID 34352228, 2021). "To confirm these observations, we looked at the specific expression of Stat genes, including the IFN-associated signal transducers and activators of transcription 1 (STAT1) and STAT2, which were both significantly underrepresented in patients with COVID-19 compared to patients with influenza." (PMID 33187979, 2020).
COVID-19 (continued). "The interferon activity is reduced in COVID-19 patients, a situation that could be normalized and balanced by ATP via the JAK/STAT-1 pathway." (PMID 33327522, 2020). "Furthermore, JAK2/STAT3 signaling contributes greatly to the cytokine storm seen in severe COVID-19 via inducing the Th1/Th17 immune response, hyperactivating STAT3 while impairing STAT1 function, thereby suppressing the antivirus interferon response and coagulopathy." (PMID 39201692, 2024). "After the identification of increased EGFR expression in COVID-19 patients, induced by lung injury and STAT1 deficit, first studies now also suggest that the usage of a specific EGFR antibody could reduce inflammation and fibrosis in severe and moderate COVID-19 patients." (PMID 37402592, 2023). "Results from extensive bioinformatics analyses in a case-control study from COVID-19-positive (n = 430) and -negative (n = 54) patients identified a signature of 13 dysregulated IFN-γ-associated genes, including STAT1 and JAK2, both key mediators of the IFN-γ signaling." (PMID 36298734, 2022). "In the context of exhaustive inflammation, we observed that TRAM-mediated STAT1/IRF7 circuitry may be involved in the expansion of Ly6C++ monocytes with elevated induction of S100a8, a key signature gene elevated in septic patients including COVID-19 patients." (PMID 35091696, 2022). "Molecularly, synergism of TNF and IFN-γ engages the janus kinase (JAK)-STAT1 axis to induce IRF1 expression and nitric oxide (NO) production, which activates PANoptosis, underscoring the importance of these molecules in the pathology of COVID-19 and other cytokine storm syndromes." (PMID 36419185, 2022). "The network constructed for comparing patients with sepsis to patients with COVID-19 ARDS also suggested an upregulation of several key molecules relevant for the pathogenesis of COVID-19 ARDS which included TLR4, IL6, and - in particular - STAT1 (signal transducer and activator of transcription 1)." (PMID 34956213, 2021). "Therefore, examining the expression features of LCN2, STAT1 and UBE2L6 in different clinical contexts such as age, gender and smoking status could help us learn more about the pathogenesis of COVID-19 in different populations." (PMID 33242255, 2020). "Interestingly, although JAK2 and STAT1, two of the main genes involved in the IFN-γ canonical pathway, presented a positive and significant correlation for non-COVID19 (r = 0.390, p < 0.01), this correlation was significantly increased in COVID-19-positive patients (r = 0.82, p < 0.001) patients." (PMID 36298734, 2022). "Bioinformatics analyses showed upregulation of MAP2K6, CBL, RUNX3, STAT1, and JAK2 in COVID-19-positive vs. -negative patients." (PMID 36298734, 2022). "Both inflammatory macrophage states showed high expression of transcription factors that promote a pro-inflammatory macrophage phenotype, STAT1 and IRF1, in inflamed RA, UC, CD, and COVID-19 BALF relative to healthy or non-inflamed tissues." (PMID 33879239, 2021). "We found that the expression of STAT1, STAT2, and IRF1 was indistinguishable among cells from control WHO 0, control WHO 7–8, and COVID-19 WHO 6–8 participants." (PMID 34352228, 2021). "Neither EIF2AK2 nor IFN-responsive transcription factors such as STAT1 and STAT2 were expressed within SARS-CoV-2 RNA+ cells from participants who developed severe COVID-19." (PMID 34352228, 2021). "In the moderate COVID-19 group, two patients had weakly neutralizing anti-IFN-α autoantibodies, with IC50 values between 100 and 350; however, these antibodies did not inhibit STAT1 phosphorylation." (PMID 40733719, 2025). "In addition, there was a patient with STAT1 gain-of-function (GOF) (P21, 15-years-old male) who developed an atypical Guillain-Barre 7 to 9 months after COVID-19 when re-exposed to SARS-CoV-2 infection (but without microbiological confirmation of infection)." (PMID 36742319, 2023).
chronic mucocutaneous candidiasis (96 papers, 2013 to 2025). "Autosomal dominant- GOF variants in STAT1 are among the commonest monogenic defects linked to chronic mucocutaneous candidiasis (CMC), with over 400 reported cases." (PMID 40666020, 2025). "This patient carries a STAT1 gain-of-function mutation, which increases the risk of chronic mucocutaneous candidiasis." (PMID 41256184, 2025). "Autosomal dominant gain-of-function (GOF) mutations in signal transducer and activator of transcription 1 (STAT1) were identified in 2011 as a cause of chronic mucocutaneous candidiasis." (PMID 41142635, 2025). "Here, we show that patients with STAT1 gain-of-function mutations and chronic mucocutaneous candidiasis have a numerically normal but functionally altered pool of C. albicans-specific Th cells, skewed toward Th1 and Th2." (PMID 41054009, 2025). "This woman had chronic mucocutaneous candidiasis owing to heterozygosity for a pathogenic gain-of-function variant in the STAT1 gene and endorsed diagnoses of Hashimoto disease, seronegative rheumatoid arthritis, and hemolytic anemia." (PMID 40816829, 2025). "The A267V variant in STAT1 has been reported in >10 individuals with chronic mucocutaneous candidiasis (CMC) and segregated with disease in 16 individuals from nine families." (PMID 40149454, 2025). "Heterozygous STAT1 gain of function (GOF) variants in patients with chronic mucocutaneous candidiasis (CMC) are associated with PD-L1 overexpression and diminished TH17 activity." (PMID 41249721, 2025). "In patients with STAT1 gain-of-function mutations, chronic mucocutaneous candidiasis was associated with frequent autoimmune endocrine disease, most often Hashimoto thyroiditis (2 of 4 cases, 50%)." (PMID 41394846, 2025). "STAT1 GOF mutations lead to interference with STAT1 dephosphorylation, leading to enhanced interferon signaling manifests, chronic mucocutaneous candidiasis and autoimmunity." (PMID 40410684, 2025). "Germline gain-of-function (GOF) mutations in signal transducer and activator of transcription 1 (STAT1) are associated with infections, including chronic mucocutaneous candidiasis and autoimmunity." (PMID 41142635, 2025). "Gain-of-function (GOF) mutations in STAT1 cause a combined immunodeficiency characterized by chronic mucocutaneous candidiasis (CMC), recurrent infections, and autoimmunity." (PMID 41394881, 2025). "The autosomal dominant form of chronic mucocutaneous candidiasis (CMC) results from STAT1 GOF pathogenic variants (OMIM #614162 and orphan designation ORPHA1334)." (PMID 39114664, 2024). "Here we report three cases of chronic mucocutaneous candidiasis with infections and autoimmunity caused by STAT1 GOF alterations." (PMID 36050429, 2023). "Leiding analyzed one STAT1 R274W case, diagnosed with chronic mucocutaneous candidiasis, mycotic cerebral aneurysms, and pneumonia (caused by H. influenzae, P. aeruginosa, S. pneumoniae), showing T cell lymphopenia." (PMID 36891307, 2023). "STAT1 Gain-of-Function (GOF) is an autosomal dominant disorder caused by several mutations that lead to STAT1 hyperphosphorylation, subsequent autoimmunity, and increased susceptibility to infection, notably chronic mucocutaneous candidiasis." (PMID 37622085, 2023). "STAT1 mutations are predominately associated with chronic mucocutaneous candidiasis and invasive mycosis." (PMID 36891307, 2023). "The clinical manifestations associated with STAT1 mutations are unexpectedly broad, including chronic mucocutaneous candidiasis, and susceptibility to various viruses, bacteria, and invasive fungi." (PMID 36891307, 2023). "Given that the E169A substitution mutation has been described in two patients diagnosed with chronic mucocutaneous candidiasis, it is evident that the proposed auto-inhibitory mechanism of STAT1 inactivation has great clinical significance." (PMID 37430250, 2023).
chronic mucocutaneous candidiasis (continued). "Patients with STAT1 gain-of-function (GOF) mutations suffer from an inborn error of immunity hallmarked by chronic mucocutaneous candidiasis (CMC)." (PMID 36172362, 2022). "Gain-of-function mutations in the STAT1 gene have been initially associated with chronic mucocutaneous candidiasis." (PMID 36102410, 2022). "On the other hand, as a result of STAT1 hyperactivation and defective nuclear dephosphorylation, mutations in the STAT1 gene trigger chronic mucocutaneous candidiasis and adversely affect Th1 and Th17 cell responses." (PMID 35883021, 2022). "Among patients with chronic mucocutaneous candidiasis phenotype, gain-of-function variants in STAT1 gene were identified in 4 patients." (PMID 35482138, 2022). "AD GOF STAT1 mutations are frequently associated with chronic mucocutaneous candidiasis (CMC), immunodeficiency, and autoimmune phenomena, accompanied by increased expression of IFN-stimulated genes (ISGs) and reduced T-helper cell type 17 (TH17) responses." (PMID 33442967, 2021). "In humans, several forms of inherited STAT1 deficiencies are associated with a high susceptibility to intracellular bacteria and viruses, while some gain-of-function STAT1 mutations are responsible for the development of chronic mucocutaneous candidiasis." (PMID 33525590, 2021). "Heterozygous STAT1 gain-of-function (GOF) mutations form the most common genetic cause of chronic mucocutaneous candidiasis (CMC)." (PMID 31068927, 2019). "We previously reported 3 pediatric patients with T. marneffei infection and chronic mucocutaneous candidiasis (CMC) caused by GOF STAT1 mutations." (PMID 31572394, 2019). "The immunological networks activated in trained monocytes depend on STAT1 activation, and defects in trained immunity have been reported in patients with chronic mucocutaneous candidiasis due to STAT1 mutations." (PMID 29755450, 2018). "As STAT1 mutations cause dominant chronic mucocutaneous candidiasis and decreased STAT1 levels in monocytes of autoimmune polyglandular syndrome 1 (APS-1) patients, it was important to further characterize AIRE–STAT1 interactions." (PMID 30002654, 2018). "Heterozygous gain-of-function (GOF) mutations in STAT1 have been associated with a diverse phenotype encompassing chronic mucocutaneous candidiasis (CMCC) and declining immunity." (PMID 30131873, 2018). "In humans, failure to generate effective Th17 responses (as a result of a range of mutations in, for example, IL-17RA, IL-17F, STAT1 genes) can result in chronic mucocutaneous candidiasis (CMC)." (PMID 26124761, 2015). "Another case series from the United Kingdom described six patients with carried a gain-of-function STAT1 mutation (GOF-STAT1) which predisposed them to inherited chronic mucocutaneous candidiasis—two of which developed and died of squamocellular esophageal carcinoma." (PMID 37374978, 2023). "Interestingly, gain-of-function mutations in STAT1 inhibit Th17 responses and cause chronic mucocutaneous candidiasis that mimics Th17-mediated immunodeficiencies." (PMID 38039135, 2023). "Autosomal dominant Signal transducer and activator of transcription 1 (STAT1) gain-of-function (GOF) mutations result in an inborn error of immunity characterized by chronic mucocutaneous candidiasis, recurrent viral and bacterial infections, and diverse autoimmune manifestations." (PMID 37020552, 2023). "Interestingly, STAT family members often cross-inhibit each other, and the hallmark clinical manifestation of STAT1 GOF is chronic mucocutaneous candidiasis (CMC), resulting from impaired Th17 differentiation due to partial STAT3 loss of function." (PMID 37275873, 2023). "STAT1 mutation can inhibit the differentiation of T cells into T-helper 17 (Th17) cells, resulting in a decrease in IL-17 secretion, which is closely related to chronic mucocutaneous candidiasis and invasive mycosis." (PMID 36891307, 2023).